CX3CR1 (C-X3-C motif chemokine receptor 1)
Diseases named in the same sentence as CX3CR1 in open-access papers (continued):
Sharing a sentence is not in itself a finding about the gene and the disease.
ischemia (21 papers, 2006 to 2024). A hypoperfusion of the BLOOD through an organ or tissue caused by a PATHOLOGIC CONSTRICTION or obstruction of its BLOOD VESSELS, or an absence of BLOOD CIRCULATION. "The deleterious consequences of CX3CR1 deficiency at late stages of pathology have been described in ischemia and SCI." (PMID 25904895, 2015). "Fumagalli and colleagues reported that, in CX3CR1-/- mice, protection from ischemia at early time points after injury is associated with a protective inflammatory milieu, characterized by the promotion of M2 polarization markers." (PMID 24490760, 2014). "Our results suggest that neuronal CX3CR1 deficiency may play a neuroprotective role in ischemia, similar to previous reports that CX3CR1 knockout protects against amyloid-β induced neurotoxicity." (PMID 29323156, 2018). "Next, we investigated whether CX3CR1 upregulation in the infarct 24 hours following pMCAO was associated with ischemia-induced neuronal apoptosis by assessing co-expression of cleaved Caspase-3 (apoptotic marker), CX3CR1, and NeuN (neuron marker) in the infarct." (PMID 29323156, 2018). "Inhibiting CX3CR1 with siRNA exacerbates ischemia‐induced microglial activation, enhances IL‐1β expression, and worsens ischemia‐induced cognitive impairment." (PMID 39691417, 2024). "The CX3CL1/CX3CR1 signaling axis promotes microglial phagocytic function in the early phase after ischemia." (PMID 34276530, 2021). "In this paper, we review literature updates and summarize the current knowledge about the opposing role of the CX3CL1/CX3CR1 signaling pathway in selected neuropathologies (including ischemia, epilepsy, and neurodegenerative diseases)." (PMID 33065974, 2020). "The number of CCR2+ monocytes peaks around day 3 post‐ischemia, whereas CX3CR1+ cells reach their peak much later, around 14–28 days after induction of ischemia." (PMID 33058417, 2020). "Conversely, other studies reported decreased release of inflammatory factors and attenuated microglial activation in the striatum of both CX3CR1-knockout (KO) and knockdown mice after experimental ischemia and in CX3CR1-KO mixed cultures." (PMID 32625064, 2020). "To examine the role of neuronal CX3CR1 in ischemia-induced neuronal cell death in vivo, we used CX3CR1−/− mice." (PMID 29323156, 2018). "Double staining with NeuN and CX3CR1 was performed and confirmed that CX3CR1 was upregulated in ipsilateral ischemia compared to the intact control, and co-localized with NeuN in most cells." (PMID 29323156, 2018). "Triple immunofluorescence staining demonstrated that CX3CR1 is co-localized in most apoptotic neurons in ischemia." (PMID 29323156, 2018). "There are also reports of early protective effects of CX3CR1 deletion in different models of acute brain injury, including ischemia, trauma, or spinal cord injury (SCI)." (PMID 25904895, 2015). "More macrophages/activated microglia infiltrated in the ischemia lesions in WT mice compared to CX3CR1-/- mice (34.1 ± 2.5% vs 15.9 ± 1.8%)." (PMID 24490760, 2014). "Using small interfering RNA (siRNA), researchers observed that inhibiting the function of CX3CR1 exacerbated the ischemia-induced chronic increase in microglia activation, enhanced the expression of IL-1beta, and worsened the ischemia-induced chronic impairment of cognition." (PMID 33065974, 2020). "Given the same early damage indicated by the magnitude of the diffusion of water molecules within the tissues shown in ADC, approximately 96.7% of the WT brains proceeded to ischemia damage as shown in T2-weighted MRI; this occurrence was only seen in 71.9% of CX3CR1−/− brains (p < 0.05)." (PMID 29323156, 2018). "Our results shed more light on the neurotoxic role of CX3CR1 in ischemia and support the hypothesis that fractalkine and its receptor are involved in a complex network of both paracrine and autocrine interactions between neurons and glia." (PMID 29323156, 2018).
ischemia (continued). "We hypothesized that CCR2+Ly6Chi inflammatory monocytes are recruited in the early phase after ischemia and transdifferentiate into CX3CR1+Ly6Clo “repair” macrophages in the brain." (PMID 27814740, 2016). "In ischemia, the neuronally expressed chemokine fractalkine may participate in the activation and chemoattraction of microglia into the injured area acting through CX3CR1." (PMID 16749930, 2006). "Furthermore, it is not possible to compare the expression levels of fractalkine/CX3CR1 after insults, as these levels were measured at different times, namely, over a period of 1 week in the acute phase of recovery vs. a period of 1 month after global ischemia." (PMID 33065974, 2020). "Our group has shown that T-lymphocytes contribute to myocardial ischaemia/reperfusion injury after primary percutaneous coronary intervention (pPCI) for ST-elevation myocardial infarction (STEMI), with the fractalkine receptor, CX3CR1, playing a central role." (PMID 34046028, 2021). "Absence of fractalkine receptor in CX3CR1-/- mice has been previously reported to be protective in ischemia." (PMID 24490760, 2014). "Since it was demonstrated that during the progression of cerebral ischemia microglia phenotype changes from anti- to pro-inflammatory and microglia express CX3CR1, we investigated whether the neuroprotective effect of CX3CL1 in ischemia is due to its ability to change the phenotype of microglia." (PMID 31607865, 2019).
Arthritis (20 papers, 2020 to 2025). Inflammation of a joint. "A recent study has reported in a mouse model of arthritis that CX3CR1+ macrophages in the synovial lining layer form an unusual protective barrier-like layer to shield the joint from inflammation associated with arthritis." (PMID 39321281, 2024). "These arthritis-associated osteoclastogenic macrophages (CX3CR1+HLA-DRhiCD11c+CD80−CD86+ cells) are present in the inflamed synovitis and are distinct from conventional osteoclast precursors in homeostatic bone remodeling." (PMID 36172385, 2022). "Recent research has identified a specific subset of macrophages, characterized by high expression of CX3CR1 and low expression of Ly6C, F4/80, and I-A/I-E, known as arthritis-associated osteoclast macrophages (AtoMs), as a precursor population of pathogenic osteoclasts in arthritis." (PMID 38799455, 2024). "Moreover, these arthritis-associated macrophages (CX3CR1+HLA-DRhiCD11c+CD80−CD86+ cells) were detected in synovial samples from human patients with RA." (PMID 36172385, 2022). "We found that arthritis activity in the D2T RA group correlated with the proportion of CX3CR1+CD4+ T cells." (PMID 39910629, 2025). "Specifically, among CX3CR1+ age-associated T cells, an increase in CD4+ T cells reflects the activity of arthritis and the degree of inflammatory markers." (PMID 39910629, 2025). "Along with an improvement in arthritis activity, the proportion of CX3CR1+CD4+ T cells decreased 24 weeks after treatment initiation." (PMID 39910629, 2025). "CX3CR1+CD4+ T cells were found to be positively correlated with arthritis activity and age in patients with D2T RA." (PMID 39910629, 2025). "Depletion of CX3CR1+ macrophages exacerbated arthritis progression and diminished the therapeutic effects of ADSCs." (PMID 40038808, 2025). "The proportion of CX3CR1+CD4+ T cells was positively correlated with arthritis activity and inflammatory marker levels." (PMID 39910629, 2025). "Upregulated genes included CX3CR1, which has been considered important to the pathogenesis of arthritis, and the CX3CR1-expressing monocytes have been associated with increased arthritic pain." (PMID 40084238, 2024). "For example, experiments in mouse models of arthritis and vincristine-induced toxicity have shown that the infiltration of blood-derived CX3CR1-expressing monocytes into the DRG drives the induction and maintenance of persistent pathological nociception." (PMID 38402219, 2024). "While studies have implicated the lining CX3Cr1+ macrophages in maintaining joint homeostasis and suppressing chronic arthritis, a recent study confirmed that they do initiate MSU crystals induced arthritis." (PMID 35874765, 2022). "Depleting of the synovial CX3CR1+TREM2+ macrophages aggravated the arthritis in K/BxN STA murine models." (PMID 35874765, 2022). "Taken together, these findings indicate that the sFasL–DR5 interaction promotes arthritis by regulating the CX3CL1–CX3CR1 axis, which increases CCL2, CCL3, and CXCL10 production by CX3CR1+ immune cells." (PMID 34223817, 2021). "In SPL of control mice, virtually all OCPs were double positive, with the increase in CCR2+CX3CR1- cell frequency in arthritis (right)." (PMID 34925336, 2021). "We found that blockade of FasL or CX3CR1 at different phases of AIA significantly attenuated arthritis and chemokine production in the joints." (PMID 34223817, 2021). "Exploring the origin of increased macrophage numbers during arthritis, the authors identified a CX3CR1+ macrophage subset in direct proximity with collagen VI expressing synovial fibroblast cells." (PMID 34211470, 2021). "At the onset of arthritis CX3CR1+ macrophages underwent altered morphology, and their cell-to-cell contacts were abrogated." (PMID 34211470, 2021). "The proportions of CX3CR1+CD4+ T cells positively correlated with arthritis activity in LORA." (PMID 39910629, 2025).
Arthritis (continued). "Thus, we injected anti-FasL or anti-CX3CR1 antibodies into mice with AIA to investigate any therapeutic effects on arthritis." (PMID 34223817, 2021). "Also, a recent study using a murine model of K/BxN serum-transfer arthritis showed that Axl was expressed by a distinct subset of CX3CR1+ tissue-resident macrophages, which form an internal immunological barrier at the synovial lining." (PMID 32964059, 2020). "In this study, we explored the therapeutic effects and mechanisms of ADSCs in a mouse model of serum transfer-induced arthritis (STA), focusing on the dynamic regulation of the CX3CR1+ synovial macrophage barrier status." (PMID 40038808, 2025). "These clusters expanded during the progression of arthritis and displayed a pro-inflammatory activation profile, including the expression of IL1-β, while CX3CR1+ still maintained their immune-regulatory phenotype." (PMID 35955514, 2022). "Therefore this study provided sufficient evidence for people to believe that CX3CR1+ synovial resident macrophages initiate and drive MSU crystal-induced arthritis." (PMID 35874765, 2022). "In fact, in K/BxN STIA, although systemic clodronate-mediated depletion of macrophages resulted in a drastic amelioration of the arthritis, CCR2 deficiency did not alter arthritis development whereas CX3CR1 deficiency produced exacerbated inflammation." (PMID 36300108, 2022). "The largest arthritis-induced increase was observed for CCR2, CCR5, and CX3CR1 expressing OCP subsets, but due to their sufficient expression in both (ctrl and CIA) groups, we selected CCR2 and CX3CR1 for further investigation." (PMID 34925336, 2021). "Furthermore, post-treatment analysis of RA showed a decrease in CX3CR1+CD4+ T cells along with an improvement in arthritis, whereas no significant changes were observed in CX3CR1+CD8+ T cells." (PMID 39910629, 2025). "Although CX3CR1 is expressed by dendritic cells which play functional roles in trans-endothelial mechanisms, dendritic cells are not critical for K/BxN arthritis progression and were not examined in this study." (PMID 36115544, 2022). "After the induction of serum-transfer arthritis (STA) and collagen-induced arthritis (CIA), CX3CR1+ lining macrophages respond by changing their morphology and spatial orientation but without proliferating, while CX3CR1– MHC-II+ sublining macrophages rapidly proliferate." (PMID 34604219, 2021).
melanoma (20 papers, 2014 to 2025). A malignant, usually aggressive tumor composed of atypical, neoplastic melanocytes. "A heightened abundance of CX3CR1 in melanoma patients, particularly associated with increased presence of CD8+ T cells, was correlated with increased overall survival probability among the individuals with melanoma." (PMID 39011040, 2024). "Analysis of single-cell datasets revealed distinct human melanoma-infiltrating CD8+ T-cell clusters expressing genes associated with effector T-cell function but with distinguishing expression of CX3CR1 or PDCD1." (PMID 38881188, 2024). "We found that the presence of the receptor of CX3CL1, CX3CR1, was associated with a significantly higher five-year survival of melanoma patients (log-rank Mantel-Cox test, p = 0.04)." (PMID 39011040, 2024). "Consistently, CX3CR1 upregulation in CD8+ T cells is associated with positive outcomes in melanoma patients." (PMID 33809259, 2021). "Moreover, CX3CR1-deficient mice injected with melanoma cells had increased tumour burden, cachexia, and defective anti-tumour responses." (PMID 39011040, 2024). "Moreover, using the B16-F10 melanoma model, the authors showed that IL-21 produced by in vitro differentiated Th17 cells also increases the frequency of CX3CR1+ CD8+ T cells in the tumor, which in turn was associated with reduced tumor burden." (PMID 33777008, 2021). "In melanoma and pancreatic cancer models, T cells transduced with CX3CR1 demonstrated improved T-cell trafficking to tumors and inhibition of tumor growth." (PMID 41181132, 2025). "Yan and colleagues reported that carboplatin and paclitaxel chemotherapies increased CX3CR1+CD8+ T cells in patients with melanoma that subsequently responded to anti-PD-1 ICB." (PMID 39343508, 2024). "Our study provides new insights into the clinical and immunological relevance of CX3CR1 expression in the tumor microenvironment of melanoma." (PMID 38881188, 2024). "Our study and others have reported subsets of CD8+ T cells expressing CX3CR1 in human melanoma tissues." (PMID 38881188, 2024). "In this study, we evaluated the frequency, transcriptomic states, and clinical relevance of CX3CR1+ CD8+ T cells in human melanoma using resected specimens and publicly available single-cell data." (PMID 38881188, 2024). "Paired sc-RNA and sc-TCR-seq analysis of melanoma patient specimens demonstrated that clonal T cells in periphery are in a more activated cellular state (CCL5+GZMB+KLRG1+KLRK1+CX3CR1+) than their counterparts in TME (PD-1+LAG3+CTLA-4+TIM-3+TIGIT+)." (PMID 37881432, 2023). "Recently, adoptive transfer studies of CX3CR1+ CD8+ T cells in a melanoma mouse model significantly suppressed tumor growth." (PMID 38127790, 2023). "Our group has previously shown that IL-21-producing CD4+ T cells provide critical help to promote the generation of effector CX3CR1+ CD8+ T cells in a preclinical melanoma model." (PMID 33809259, 2021). "Finally, a high expression level of CX3CR1 in melanoma patients was correlated with increased abundance of cytotoxic CD8+ T-cells." (PMID 39011040, 2024). "Furthermore, analysis of melanoma patient data revealed enhanced survival rates in individuals exhibiting elevated levels of CD8+ T cells expressing CX3CR1." (PMID 39011040, 2024). "Furthermore, analysis of the TCGA-SKCM database of data from 98 melanoma patients revealed a significant correlation between increased CX3CR1 expression and the patients’ improved overall survival probability." (PMID 39011040, 2024). "In addition, an increase in CX3CR1 expression was correlated with increased overall survival probability of melanoma patients and increased CD8+ T cell signature." (PMID 39011040, 2024). "The expression of PD-1 and TIGIT in the CX3CR1+ subset was substantially lower than that in the CX3CR1− subset in the tumor microenvironment, in agreement with the scRNA-seq analyses of human melanoma." (PMID 38881188, 2024).
melanoma (continued). "Moreover, using surgically resected specimens and a publicly available database of human melanomas, we have provided insights into the frequency, transcriptomic signatures, and clinical relevance of CX3CR1+ CD8+ T cells in human melanomas." (PMID 38881188, 2024). "In addition, analysis of publicly available human database (The Cancer Genome Atlas-Skin Cutaneous Melanoma (TCGA-SKCM)) containing data from 98 melanoma patients revealed a correlation between high levels of CX3CR1 expression and higher overall survival probability." (PMID 39011040, 2024). "Of note, TIL-TCRs expanded in response to chemo-immunotherapy could be identified within the same cluster expressing CX3CR1 at pretreatment in line with recent studies evaluating the tumor and a time-matched blood sample from patients with melanoma with scRNA/TCR-seq." (PMID 37009132, 2023). "Using 2PM imaging, we found that CX3CR1+ SCS macrophages take up subcellular-sized particles containing a cytoplasmic fluorescent fusion protein produced by B16 melanoma cells, which may represent apoptotic bodies from the primary tumor site or tumor-derived microvesicles." (PMID 25821451, 2015). "Cytotoxic NK cells accumulate at tumor margins in a CX3CR1-dependent manner following exposure to immune checkpoint blockade (ICB), and NK cell depletion enhances CD8+ T-cell infiltration into melanoma and overcomes ICB resistance." (PMID 40530504, 2025). "When melanoma first enters the brain, it encounters an environment dominated by micro-glial cells, which express the receptors TREM2, CX3CR1, and complement receptors." (PMID 41463339, 2025). "Here, we sought to examine the generation, transcriptomic states, and the clinical relevance of melanoma-infiltrating CD8+ T cells expressing a chemokine receptor and T-cell differentiation marker, CX3C chemokine receptor 1 (CX3CR1)." (PMID 38881188, 2024). "In another melanoma study, increased CD8+ Tem expressing CX3CR1 was shown in patients responding to ICBs, and this subset has effector memory phenotypes and cytotoxic activity." (PMID 37881432, 2023). "Others identified increased frequencies of CX3CR1+ CD8+ T cells in non-small cell lung and melanoma patients who responded to anti-PD-1 therapy, where these cells exhibited migratory capabilities into the tumor site followed by potent tumor rejection." (PMID 38127790, 2023). "Using Pf4 Cx3cr1 mice to deplete CD206hi IMs expressing Cxcl13, Cxcl9, and Cxcl10, we demonstrate their essential role in TLS formation, lymphocyte recruitment, and tumor suppression in melanoma and lung adenocarcinoma." (PMID 40630529, 2025). "Furthermore, thorough analysis of the TCGA-SKCM public dataset from 98 melanoma patients revealed the role of CX3CL1 and its receptor CX3CR1 in melanoma patients." (PMID 39011040, 2024). "No obvious impact of CX3CR1 expression in melanoma on the response to immune checkpoint inhibitor therapy was observed while increased pretreatment and on-treatment frequency of a CD8+ T-cell cluster expressing high levels of exhaustion markers was associated with poor response to the treatment." (PMID 38881188, 2024). "In this study, using a preclinical model of melanoma that lacks CX3CL1 expression and tumor-specific CD8+ T cells in which the CX3CR1 gene was replaced with a functionally unrelated gene, we have demonstrated the intratumoral generation of antigen-specific CX3CR1+ CD8+ T cells." (PMID 38881188, 2024). "CX3CR1 was stably expressed on differentiated CD8+ T cells in the effector phase, and increased frequency of circulating CX3CR1+CD8+ T cells correlated with response to anti-PD-1 therapy in patients with renal cell carcinoma, melanoma, and non-small cell lung cancer." (PMID 37509302, 2023).